SELENBP1 (selenium binding protein 1)
Diseases named in the same sentence as SELENBP1 in open-access papers (continued):
Sharing a sentence is not in itself a finding about the gene and the disease.
breast carcinoma (12 papers, 2013 to 2024). "Low expression of SELENBP1 in patients with ER+ breast cancer was significantly associated with poor survival." (PMID 38785550, 2024). "Low SELENBP1 expression in ER+ breast cancer patients was significantly associated with poor survival (p<0.01), and SELENBP1 levels progressively decreased with advancing clinical stages of breast cancer." (PMID 23704933, 2013). "SELENBP1 expression is associated with poor prognosis in several cancer types, including lung adenocarcinoma, hepatocellular carcinoma, and colorectal carcinogenesis, as well as breast cancer." (PMID 35205284, 2022). "Moreover, within ER+ breast cancer patients, higher SELENBP1 expression was significantly associated with better survival than lower expression (p = 0.011, log-ranked test)." (PMID 23704933, 2013). "To clarify whether levels of SELENBP1 expression are associated with ER status in breast cancer, we analyzed SELENBP1 expression levels with respect to ER+ and ER– samples as well as the patient survival within the ER+ patients." (PMID 23704933, 2013). "Our data indicate that SELENBP1 could be an underestimated important marker for predicting patient survival, a marker to predict effective selenium prevention in breast cancer high risk patients and treatment in breast cancer patients." (PMID 23704933, 2013). "SELENBP1 was reduced in breast cancer tissues compared to normal controls; hence, the expression level of SELENBP1 can be used as an essential indicator to predict the efficacy of Se supplementation and survival in breast cancer patients." (PMID 36770890, 2023). "Lower SELENBP1 expression in breast cancer tissues compared to normal control is significantly associated with poor survival (p < 0.01)." (PMID 36386843, 2022). "SELENBP1 has been shown to be expressed at low levels in cancers such as renal cell carcinoma, lung adenocarcinoma, and breast cancer and is generally predictive of poor clinical outcomes." (PMID 34566889, 2021). "In a study of breast cancer samples, the level of SELENBP1 was decreased in tumor tissues compared with normal tissues and correlated with late disease stages and poor survival." (PMID 25227434, 2014). "This is the first study to reveal the importance of monitoring SELENBP1 expression as a potential biomarker in contributing to breast cancer prevention and treatment." (PMID 23704933, 2013). "High levels of SELENBP1 expression found in ER+ and luminal breast cancer cells can be downregulated by addition of exogenous estrogen." (PMID 23704933, 2013). "The expression level of SELENBP1 in ER– breast cancer tissues was significantly lower than in ER+ tissues (4.44±2.62 versus 6.61±1.28, p = 0.000)." (PMID 23704933, 2013). "We examined SELENBP1 expression levels in a panel of breast cancer cell lines which included 4 ER+ (MCF7, BT474, ZR75B, and T47D) and 7 ER– cell lines (HCC1937, SKBR3, HCC70, MB453, MB468, MB231, HS578T)." (PMID 23704933, 2013). "In our tissue array staining of breast cancer samples, the level of SELENBP1 expression was decreased in tumor tissues compared to normal, which is consistent with previous reports." (PMID 23704933, 2013). "In support of the clinical data, a similar expression pattern was observed for SELENBP1 in 12 commonly used breast cancer cell lines." (PMID 23704933, 2013). "In summary, we found that reduced SELENBP1 expression in breast cancer correlated with late stages of the disease and poor survival." (PMID 23704933, 2013). "We found that patients in stage III of breast cancer had the biggest decrease of SELENBP1 expression (5.06±2.34) among the three groups." (PMID 23704933, 2013). "We also found that estrogen levels are another important factor for breast cancer prevention and treatment through a novel pathway involving SELENBP1 downregulation." (PMID 23704933, 2013).
breast carcinoma (continued). "In ER+ SELENBP1 high expressing breast cancer cells, addition of exogenous estrogen downregulated SELENBP1 expression, and knocking down SELENBP1 confers the cell resistance to selenium treated cell proliferation inhibition." (PMID 23704933, 2013). "In ER+ breast cancer cells, we found that SELENBP1 expression was reduced upon exogenous estrogen treatment." (PMID 23704933, 2013). "Decrease of SELENBP1 expression upon estrogen treatment or silencing SELENBP1 rendered ER+ breast cancer cells resistant to selenium treatment." (PMID 23704933, 2013). "In ER+ and luminal breast cancer cells, pathological level of estrogen in serum and tissue fluids promote carcinogenesis and tumor growth by decreasing SELENBP1 expression, subsequently abolishing the anti-tumor effect of selenium." (PMID 23704933, 2013). "In particular, SELENBP1 expression is reduced in breast cancer tissues compared to normal controls." (PMID 38785550, 2024). "And previous studies have indicated that SELENBP1 performed an important role in the inhibition of cell proliferation in breast cancer and gastric cancer cells treated with selenium, suggesting that SELENBP1 was one of the mediators for the antitumor effect of selenium." (PMID 37606338, 2023). "Moreover, SELENBP1 re-expression results in diminished cancer cell proliferation and migration, and an induction of apoptosis in colorectal and breast cancer." (PMID 29535818, 2018). "In this study, we determined the levels of SELENBP1 expression in breast cancer tissue arrays; we show the correlation of SELENBP1 expression with other known breast cancer markers as well as uncover a correlation between SELENBP1 expression and patient survival." (PMID 23704933, 2013). "In addition, we determined that estrogen is responsible for the regulation of SELENBP1, and we demonstrate the functional role of SELENBP1 in the proliferation of breast cancer cell lines with Se-treatment." (PMID 23704933, 2013). "We found that SELENBP1 expression in breast cancer tissues is reduced compared to normal control." (PMID 23704933, 2013). "Thus, our data indicate that basal and luminal breast cancer cells that are resistant to the Selenium’s cancer prevention and treatment effects are most probably due to downregulated SELENBP1." (PMID 23704933, 2013). "While among the ER+ breast cancer cell lines, varying levels of SELENBP1 expression were found." (PMID 23704933, 2013). "Thus, the level of SELENBP1 expression is reduced throughout the progression of pathogenesis of breast cancer, which is a later event and is also correlated with ER status." (PMID 23704933, 2013). "All 6 luminal type breast cancer cells expressed certain levels of SELENBP1." (PMID 23704933, 2013). "Thus, the expression level of SELENBP1 may be an important marker for predicting survival and the effectiveness of selenium supplementation in breast cancer." (PMID 38785550, 2024). "Therefore, the expression level of SELENBP1 could be an important marker for predicting survival and effectiveness of selenium supplementation in breast cancer." (PMID 23704933, 2013). "SELENBP1 interacts with the nuclear receptor estrogen receptor 2 (ESR2, ERβ) to modulate cell proliferation and tumor growth in breast cancer." (PMID 36386843, 2022). "The levels of SELENBP1 resulted to be down-expressed in the TNBC cells compared to other breast cancer cellular subtypes, confirming the inverse correlation between GPX1 and SELENBP1 levels in TNBC cells." (PMID 35158912, 2022). "SELENBP1 regulates GPX1 expression in hepatocellular carcinoma (HCC), breast cancer, colon cancer, and skin cancer." (PMID 36386843, 2022). "Based on the results of screening of 12 breast cancer cell lines, we chose MCF7, T47D, SKBR3 and MB453 cells as representatives of different ER status in breast cancer cells but all have high SELENBP1 expression for further studies." (PMID 23704933, 2013).
breast carcinoma (continued). "However, the significance of SELENBP1 expression in breast cancer is still largely unknown." (PMID 23704933, 2013). "SELENBP1 can also interact with the retinoid-receptor RARα in the nuclear material, whose interaction is reduced by all trans-retinoic acid (ATRA, a cancer drug) in the breast cancer cell line." (PMID 36386843, 2022). "The interaction between SELENBP1 and GPX1 is found in MCF-7 breast carcinoma cells." (PMID 36386843, 2022). "In our results, SELENBP1 expression was lower in breast cancer samples in the nonobese group than in the obese group." (PMID 34566889, 2021). "As example, breast cancer cells without MSA treatment did not display altered proliferation potential upon transfection with a SELENBP1 plasmid." (PMID 29535818, 2018). "Selenium-mediated inhibition of breast cancer growth was compared between the cell line with high endogenous SELENBP1 (MCF7 transfected with shRNA vector control) and SELENBP1 knock-down cells (MCF7 transfected with SELENBP1-specific shRNA)." (PMID 23704933, 2013). "In ER silenced SELENBP1 high expressing breast cancer cells, E2 treatment does not affect the cell proliferation inhibition ability of selenium treatment." (PMID 23704933, 2013). "ER– and basal cells of breast cancer are resistant to selenium-mediated effects on cancer because of little to no level of SELENBP1 expression." (PMID 23704933, 2013). "Among estrogen-responsive genes found in previous studies, mRNA levels of SELENBP1, but not other selenium-containing proteins, were found to be down-regulated by estrogen treatment in breast cancer cells." (PMID 23704933, 2013). "Generally, most of the ER– breast cancer cell lines were found to express little to no SELENBP1 when compared with ER+ breast cancer cell lines." (PMID 23704933, 2013). "To determine whether estrogen can modulate SELENBP1 expression in ER+ (MCF7 and T47D cells) and ER– (SKBR3 and MB453 cells) breast cancer cells, we treated the cells with 17β-estrodial (E2) in complete media containing charcoal-stripped FBS for different length of times." (PMID 23704933, 2013). "This may indicate that SELENBP1 is mostly expressed in ER+ and luminal breast cancer cells but not ER– and basal breast cancer cells which are more aggressive cell lines." (PMID 23704933, 2013). "Nevertheless, the biological functions SELENBP1 plays in breast cancer have not been explored." (PMID 23704933, 2013).
prostate carcinoma (10 papers, 2010 to 2023). A carcinoma that arises from epithelial cells of the prostate gland. "In prostate cancer, low levels of SELENBP1 were suggestively associated with increased Gleason Score and poor clinical outcome." (PMID 25227434, 2014). "SELENBP1 may influence the plasma selenium levels and may be associated with the risk of advanced prostate cancer." (PMID 36386843, 2022). "Studies have shown significant downregulation of SELENBP1 in many types of cancer, including lung cancer, gastric cancer, prostate cancer, and HNSC." (PMID 36718148, 2023). "Then, EED recruits polycomb repressive complexes 1 (PRC1) directly to the tri-methylated H3K27 loci and enhances PRC1-mediated H2A ubiquitin E3 ligase activity, indicating a potential role for SELENBP1 as an epigenetic exchange factor in prostate cancer." (PMID 36386843, 2022). "SELENBP1 is suppressed in several human cancers including cancers of the prostate, lung, breast and ovary." (PMID 29535818, 2018). "In addition, HNF4 alpha, a novel transcriptional inhibitor of SELENBP1, plays a role in prostate cancer by binding to the SELENBP1 promoter region." (PMID 36386843, 2022). "Prostate cancer: SELENBP1 is observed to be at lower levels in prostate cancer." (PMID 36386843, 2022). "The interaction between USP33 and SELENBP1 was detected by a two-hybrid assay in human prostate cancer cells, indicating SELENBP1 may play a role in epigenetics regulation." (PMID 36386843, 2022). "GPx enzyme activity is inversely correlated with SELENBP1 levels in prostate cancer tissue." (PMID 36386843, 2022). "In human prostate cancer cells, SELENBP1 interacts with von Hippel–Lindau protein (pVHL)-interacting deubiquitinating enzyme 1 (VDU1), and VUD1 incorporates selenium into SELENBP1." (PMID 36386843, 2022). "Other downregulated genes, including SELENBP1 and IGFBP7, seen in CAFs have previously been reported to be tumor suppressors with proapoptotic and antiproliferative effects on prostate cancer cells." (PMID 28831065, 2017). "Notably, SELENBP1 also seems to interact with HIF-1; the mouse homolog of SELENBP1 has been identified as a HIF-1 target gene, and SELENBP1 has been shown to negatively regulate the alpha subunit of HIF-1 in LNCaP prostate cancer cells." (PMID 38001780, 2023). "But the downregulated expression of SELENBP1 was shown to restrain the activation of AMPK signaling and increased oxidative phosphorylation level, changed the energy metabolism pattern, and promoted the development of prostate cancer." (PMID 37606338, 2023). "SELENBP1 interacts with embryonic ectoderm development (EED), a core component of polycomb group proteins in the nuclear material of VCaP (vertebral cancer of the prostate) cells, a prostate cancer cell line." (PMID 36386843, 2022). "As to energy metabolism, SELENBP1 produces H2O2 and H2S and consequential activation of AMP-activated protein kinase (AMPK), a major regulator of energy homeostasis as well as inhibited oxidative phosphorylation (OXPHOS) in prostate cancer cells." (PMID 36386843, 2022).
colon carcinoma (9 papers, 2010 to 2023). "Although loss of SELENBP1 expression may be secondary to tumor development, the ability of SELENBP1 to inhibit cell proliferation and induce apoptosis in colon cancer may suggest that the protein may also be involved in tumorigenesis of uterine leiomyoma." (PMID 21143902, 2010). "Nevertheless, HCT116 colon carcinoma cells overexpressing a Cys57Gly mutant of SELENBP1 were reported to be less protected against selenite toxicity than cells overexpressing the wildtype protein." (PMID 37437449, 2023). "Based on the Ualcan database, we found that SELENBP1 protein expression was also decreased in colon cancer." (PMID 36253721, 2022). "Colon cancer: In colon cancer, the promoter of SELENBP1 was methylated in both human colon tissues and cell lines (HCT116, SW480, Caco-2, and HT-29 cells), while it was mostly unmethylated in LS174T cells." (PMID 36386843, 2022). "SELENBP1 induces H2O2-mediated apoptosis in colon cancer cells and inhibits cancer cell migration in vitro and tumor growth in vivo." (PMID 36386843, 2022). "SELENBP1 is an intracellular transporter protein for selenium, it has also been known to be a tumor suppressor in colon cancer." (PMID 28938569, 2017). "Colon cancer: SELENBP1 is downregulated in the proteomic analysis of colorectal cancer (CRC)." (PMID 36386843, 2022). "In esophageal adenocarcinoma and colon cancer, histone deacetylase inhibitors or demethylating agents could target SELENBP1 expression." (PMID 36386843, 2022). "However, very little methylation in the SELENBP1 promoter was detected in the colon cancer cell line SW480 in another study." (PMID 36386843, 2022). "To verify this notion, we established stable transfectants expressing HA-tagged SELENBP1 protein in human colon cancer HCT116 wild-type cells (HCT116 WT) and p21 knockout cells (HCT116 p21−/−), in both of which endogenous protein levels of SELENBP1 were undetectable." (PMID 31918717, 2020). "Similarly, reduced levels of SELENBP1 are an indicator of poor prognosis in colon cancer." (PMID 25227434, 2014).
lung adenocarcinoma (9 papers, 2010 to 2025). A carcinoma that arises from the lung and is characterized by the presence of malignant glandular epithelial cells. "SELENBP1 was demonstrated to be involved in the tumor growth-suppressive effects of Nkx2-1, and it was reported to inhibit tumor growth and the migration of lung adenocarcinoma." (PMID 35205284, 2022). "SELENBP1 is regulated by Nkx2-1 in lung adenocarcinoma in both the human lung adenocarcinoma and mouse lung cancer model." (PMID 36386843, 2022). "Using quantitative two-dimensional polyacrylamide gel electrophoresis (2-D PAGE), two isoforms of SELENBP1 are significantly decreased in lung adenocarcinomas at both mRNA and protein levels." (PMID 36386843, 2022). "Up to now, to our knowledge, only one study demonstrated that the downregulated expression of SELENBP1 could notably increase the clonal growth and migration of mice lung adenocarcinoma cells 394 T4 in vitro, and promote 394 T4 cells growth in vivo." (PMID 37606338, 2023). "After careful literature research, we found that SELENBP1 that owned lower expression in the low AIDPS group with poor prognosis was associated with better tumor prognosis, and its decreased expression led to poor prognosis of many tumors such as lung adenocarcinoma." (PMID 36282174, 2022). "Up-regulation of SELENBP1 expression inhibits the activation of PI3K/AKT/mTOR signaling pathway, thereby hindering the malignant development of lung adenocarcinoma." (PMID 40732347, 2025). "A negative correlation between SELENBP1 expression and Ki67 positivity has been reported in lung adenocarcinomas, but our study did not reveal a significant relationship between SELENBP1 expression and proliferation index in uterine leiomyomas." (PMID 21143902, 2010). "Although previous studies have suggested that SELENBP1 may exert tumor-suppressive functions, its role in lung adenocarcinoma (LUAD) has not been systematically elucidated, and the underlying mechanisms remain relatively unclear." (PMID 40787454, 2025).
hepatocellular carcinoma (8 papers, 2013 to 2024). A malignant tumor that arises from hepatocytes. "Taken together, our findings suggest that inhibition of SELENBP1 expression by HBx might act as one of the causes in the development of hepatocellular carcinoma caused by HBV infection." (PMID 32443734, 2020). "Differential expression of SELENBP1 in PBMCs of hepatocellular carcinoma patients has been established previously." (PMID 38335183, 2024). "The goal of our research was to investigate whether the treatment with selenite shows functional effects on GPX1, SELK and SELENBP1, which belong to two different classes of selenium containing molecules, and on the hepatoma cell cytokinome." (PMID 23442931, 2013). "In hepatocellular carcinoma (HCC), selenium-binding protein 1 (SBP1) and GPX1 formed nuclear bodies and colocalized under oxidative stress." (PMID 24228025, 2013). "Being one of the most common cancers worldwide, the correlation of hepatocellular carcinoma (HCC) and SELENBP1 is under investigation." (PMID 32443734, 2020). "The aim of this work was to test in vitro the effect of sodium selenite on the human hepatoma cell lines, HepG2 and Huh7, to assess its effect on the expression of GPX1, SELK and SELENBP1 and also to evaluate its action on inflammation determinants such as cytokines." (PMID 23442931, 2013).